AURKA (aurora kinase A)
Diseases named in the same sentence as AURKA in open-access papers (continued):
Sharing a sentence is not in itself a finding about the gene and the disease.
hepatocellular carcinoma (45 papers, 2007 to 2026). A malignant tumor that arises from hepatocytes. "AURKA has been studied in a wide range of human malignancies and is associated with poor prognosis in several malignancies, including cervical squamous cell carcinoma, hepatocellular carcinoma, and nonsmall cell lung carcinoma." (PMID 31087508, 2019). "AURKA is often overexpressed in hepatocellular carcinoma (HCC), making it a potential diagnostic and prognostic marker of disease severity." (PMID 38590119, 2024). "AURKA gene single nucleotide polymorphisms (SNPs) may be a biomarker for hepatocellular carcinoma." (PMID 35201446, 2021). "This study provides comprehensive computational evidence that berberine exerts anti-hepatocellular carcinoma effects through dual targeting of AURKA and CDK1, two critical cell cycle regulators frequently overexpressed in hepatocellular carcinoma." (PMID 41226349, 2025). "Berberine manifests anti-hepatocellular carcinoma activities primarily via coordinated targeting of AURKA and CDK1, essential cell cycle modulators." (PMID 41226349, 2025). "AURKA has been found to be involved in tumorigenesis, affecting cell proliferation, apoptosis, and metastasis in hepatocellular carcinoma." (PMID 39765633, 2024). "Diminished levels of miR-490 have been found in hepatocellular carcinoma, and AURKA as an established target of miR-490 was elevated." (PMID 35087589, 2022). "A link between the hypoxia response and AURKA expression was first uncovered by a group that observed increased AURKA mRNA levels upon hypoxia in HepG2 hepatoma cells, and this occurred via Hypoxia-Inducible Factor 1 (HIF-1α)." (PMID 36067794, 2022). "Previous studies showed that inhibition of AURKA would activate NF-κB signaling pathway to confer radio-resistance or chemoresistance in hepatocellular carcinoma and acute myeloid leukemia." (PMID 35078445, 2022). "Our result also showed that AURKA served as a new diagnosis and prognosis of hepatocellular carcinoma, even as also a potential and novel curcumin-related therapeutic target for hepatocellular carcinoma." (PMID 35078445, 2022). "Previous studies showed that AURKA promoted proliferation and metastasis of hepatocellular carcinoma cells." (PMID 35078445, 2022). "lncRNA TUG1 promoted hepatoma cell proliferation, migration and invasion, inhibited apoptosis, and up-regulated AURKA expression in hepatocellular carcinoma." (PMID 34039257, 2021). "MicroRNA-490-3p suppresses hepatocellular carcinoma cell proliferation and migration by targeting AURKA." (PMID 33245732, 2020). "Microarray analysis pointed out that AURKA phosphorylated and stabilized hepatoma upregulated protein." (PMID 31886176, 2019). "In studies of the mechanisms of hepatocellular carcinoma metastasis, overexpression of AURKA induces the epithelial-mesenchymal transition and CSC behaviors via the phosphatidylinositol 3-kinase/AKT pathway." (PMID 31334127, 2019). "let-7 is another modulator of AURKA that is downregulated in hepatocellular cancer." (PMID 35087589, 2022). "Interestingly, while AURKA appears to regulate MYCN's ability to bind Pol II promoters, the MYC-AURKA interaction enables hepatocellular carcinoma cells to overcome G2/M cell cycle arrest, suggesting reciprocal control." (PMID 31455158, 2019). "Destruction of AURKA or Myc inhibits the malignant phenotypes of hepatocellular carcinoma cells." (PMID 27636990, 2016).
hepatocellular carcinoma (continued). "Notably, AURKA overexpression has been significantly associated with high-grade (grade II-IV) and high-stage (stage IIIB-IV) hepatocellular carcinoma tumors." (PMID 25987188, 2015). "AURKA's dysregulation is frequently observed in various human cancers, including hepatocellular carcinoma (HCC)." (PMID 38590119, 2024). "AURKA (aurora kinase A) has been confirmed as an oncogene in cancer development including hepatocellular carcinoma (HCC)." (PMID 37773181, 2023). "Moreover, overexpressed AURKA might promote hepatocellular carcinoma cell growth, adhesion and migration in vitro." (PMID 34336648, 2021). "The mitotic serine/threonine kinase aurora kinase-A (AURKA) has been identified as carcinogenic in hepatocellular carcinoma (HCC)." (PMID 31873123, 2019). "Aurora A kinase (AURKA) is an important regulator in mitotic progression and is overexpressed frequently in human cancers, including hepatocellular carcinoma (HCC)." (PMID 31269749, 2019). "In human hepatocellular carcinoma (HCC), AURKA was found to be overexpressed at mRNA level in 61% of HCC samples, whereas gene amplification was recorded in only 3 out of 224 HCC samples." (PMID 25987188, 2015). "This study systematically elucidates the potential mechanisms of AAI, an environmental pollutant, in inducing hepatocellular carcinoma, identifying key targets including CYP1A2, ESR1, and AURKA." (PMID 40864066, 2025). "Our results provided a novel panel of AURKA, CDK1, TOP2A, CYP2C9, and CYP3A4 candidate genes for curcumin related chemotherapy of hepatocellular carcinoma." (PMID 35078445, 2022). "AURKA, CDK1, CCNB1 and TOP2A were significantly upregulated and correlated with poor prognosis in hepatocellular carcinoma, AUC values of which were 95.7, 96.9, 98.1 and 96.1% respectively." (PMID 35078445, 2022). "Not only that, the high expression of AURKA may also be a poor prognostic marker for adrenocortical carcinoma, renal clear cell carcinoma, hepatocellular carcinoma (HCC), lung adenocarcinoma (ADC), and mesothelioma." (PMID 34616431, 2021). "Microarray studies suggested that AURKA phosphorylates and stabilizes hepatoma up-regulated protein (HURP), a cell cycle regulated gene that is overexpressed in human hepatocellular carcinoma (HCC)." (PMID 25987188, 2015). "DLG7 was first identified as a potential oncogene, over-expressed in human hepatocellular carcinoma (HURP hepatoma up-regulated protein), having an expression profile well correlated to AURKA." (PMID 19753302, 2009). "Therefore, this study employed an integrated computational biology and machine learning approach to elucidate berberine’s mechanisms, identifying AURKA and CDK1 as its principal therapeutic targets against hepatocellular carcinoma." (PMID 41226349, 2025). "When we merged these hub genes with differentially expressed genes in GSE14520 dataset and differentially expressed genes of hepatocellular carcinoma in GEPIA database, seven communal genes were found, they were AURKA, CDK1, CCNB1, TOP2A, CYP3A4, CYP2C9, and CYP2B6." (PMID 35078445, 2022). "Taken these together, our results suggested that the lower dose curcumin treatment might not induced sufficient downregulation of AURKA or CDK1 to inhibit proliferation of hepatocellular carcinoma cells." (PMID 35078445, 2022). "Thus, our results indicated that curcumin might decrease the expression of AURKA, CDK1 and TOP2A to reverse chemoresistance in hepatocellular carcinoma treatment." (PMID 35078445, 2022). "Importantly, the central role of AURKA and CDK1 in hepatocellular carcinoma is corroborated by independent clinical bioinformatics analyses which also identified these kinases as prognostic biomarkers in HBV-related HCC." (PMID 41226349, 2025).
hepatocellular carcinoma (continued). "In hepatocellular carcinomas (HCC), the increased levels of AURKA do not always correlate with gene amplification." (PMID 34062959, 2021).
glioma (42 papers, 2010 to 2025). A benign or malignant brain and spinal cord tumor that arises from glial cells (astrocytes, oligodendrocytes, ependymal cells). "Diffuse intrinsic pontine glioma (DIPG) patients had significantly higher expression of AURKA compared to normal brain controls and survival analysis of pediatric patients with high-grade gliomas indicated that high AURKA expression was associated with a poorer prognosis." (PMID 37128506, 2023). "In summary, PLK1, CCNA2, CCNB2, and AURKA were screened as candidate diagnostic marker genes of glioma, and hsa-let-7b-5p could inhibit the invasion and metastasis of glioma cells." (PMID 30995921, 2019). "Similarly, high expression of CCNA2 and AURKA was associated with a worse overall survival (OS) of glioma patients." (PMID 30995921, 2019). "We subsequently used a mouse syngeneic glioma model with G261-Luc cells to assess the efficacy of AURKA inhibition in vivo." (PMID 39928563, 2025). "In conclusion, our study proposes an AURKA-mediated EGFR/B7-H3 regulatory mechanism in glioma cells and highlights the importance of AURKA in enhancing B7-H3–targeting immunotherapy in glioma mouse models." (PMID 39928563, 2025). "After treatment with alisertib, an AURKA-specific inhibitor, we observed a marked reduction in the proliferation of glioma cells, accompanied by an increase in B7-H3 expression." (PMID 39928563, 2025). "We present what we believe to be the first investigation into the potential of combining the AURKA inhibitor alisertib with B7-H3–specific blocking mAbs in preclinical glioma models." (PMID 39928563, 2025). "Previous studies have demonstrated that alisertib, a clinically validated specific AURKA inhibitor, suppresses the growth of various glioma cell lines." (PMID 39928563, 2025). "First, AURKA expression was detected in the human glioma cell lines LN18, U87-MG, U373, LN229, TJ906, M059K, and U251, which were used as in vitro models." (PMID 39928563, 2025). "We have analyzed the level of Reg-2 and its newly identified targets that encode the cyclins CCND1, CCNE1, CCNE2, CCNB1, CCNA2, and the kinases PLK1 and AURKA in glioma tumors." (PMID 38238463, 2024). "In glioma, inhibition of AURKA expression can inhibit the growth of tumor cells, which can be used as a potential therapeutic target." (PMID 39118481, 2024). "Previous studies have shown elevated AURKA mRNA expression in glioma, and the protein levels of the AURKA were reported to be increased in glioma." (PMID 36816802, 2023). "It has been reported that the expression of AURKA mRNA is increased in glioma, which is consistent with our results from bioinformatic analysis." (PMID 36816802, 2023). "The Gli2/miR-124/AURKA occupies an essential position during the growth and development of human glioma cells." (PMID 35201446, 2021). "In glioma cells treated with a low concentration of arsenic trioxide (2 μM), the cell cycle was blocked in G2/M phase, and the levels of cyclinB1, aurora kinase A, and phosphorylated aurora kinase A decreased in a dose-dependent manner." (PMID 32983240, 2020). "A recent Phase I study evaluated the association of stereotactic radiotherapy (FSRT) with alisertib, a 2nd generation Aurora A kinase (AURKA) inhibitor with anti-neoplastic and radio-sensitization activity, in recurrent high-grade glioma patients." (PMID 33375286, 2020). "In the present study, the expression levels of CCAN2, CCNB2, PLK1, and AURKA in glioma were upregulated, and hsa-let-7b-5p binding sites were found in four gene sequences." (PMID 30995921, 2019). "High levels of Gli2 suppress the miR-124 level, leading to increased levels of AURKA in glioma cells." (PMID 29899399, 2018). "In human glioma cells, miR-124 is a key downstream target gene of the Hh pathway, and inhibiting the Hh pathway suppresses cell growth via the Gli2/miR-124/AURKA pathway." (PMID 29899399, 2018).
glioma (continued). "Integrated DNA and RNA analysis of low-grade and high-grade proneural gliomas identified increased expression and gene amplification of several genes including GLIS3, TGFB2, TNC, AURKA, and VEGFA in proneural GBMs, with corresponding loss of DLL3 and HEY2." (PMID 20838435, 2010). "Furthermore, we confirmed in vitro that AURKA upregulation increased B7-H3 expression levels and that AURKA downregulation reduced B7-H3 expression levels in glioma cells." (PMID 39928563, 2025). "Additionally, both AURKA knockdown and overexpression resulted in parallel changes in B7-H3 expression levels in glioma cells." (PMID 39928563, 2025). "Considering our observed enhancement in NK-cell mediated elimination of GBM cells in the lab, we speculated about the potential impact of AURKA inhibition on NK-cell infiltration in gliomas." (PMID 38995006, 2024). "It is anticipated that further investigation into TRIB3 and AURKA could lead to the development of novel therapeutic targets for glioma, such as MGMT and EGFR." (PMID 39118481, 2024). "The AURKA oncogene is amplified in various tumors, including glioma." (PMID 36816802, 2023). "The transcription factor ZNF655 promoted glioma progression by binding to the promoter of AURKA." (PMID 36518188, 2022). "Because of striking morphological changes (data not shown) in glioma cells depleted of either aurora kinase A, aurora kinase B, or aurora kinase C, we investigated the function in vitro." (PMID 34058053, 2022). "Existing research demonstrated that Gli2/miR-124/AURKA axis might be the key to influencing AURKA’s effect on glioma." (PMID 35201446, 2021). "AURKA expression levels correlate with malignancy grade in gliomas." (PMID 31969990, 2020). "The results showed that hsa-let-7b-5p could regulate target genes, including cell cycle protein A2 (CCNA2), CCNB2, PLK1, and AURKA, and further affect the progress of glioma." (PMID 30995921, 2019). "For example, miR-124, an important downstream target gene of hedgehog (Hh) signaling, potentially interacts with the 3′-UTR region of AURKA; thus, upregulating miR-124 significantly reduces the expression of AURKA and inhibits the proliferation and growth of human glioma cells." (PMID 30405856, 2018). "Also in glioma-initiating cells (distinguished by their capacity of self-renewal) AURKA is a negative regulator of β-catenin, by binding to AXIN120." (PMID 29760449, 2018). "Moreover, AURKA is strongly correlated with survival of glioma stem cells." (PMID 26466313, 2015). "Mechanistically, AURKA elevated B7-H3 expression by promoting epidermal growth factor receptor (EGFR) phosphorylation, which was validated in glioma cell lines and primary GBM cells." (PMID 39928563, 2025). "In this study, we demonstrated a strong correlation between aurora kinase A (AURKA) and CD276 expression in glioma tissue samples." (PMID 39928563, 2025). "In this study, by analyzing the Chinese Glioma Genome Atlas (CGGA) and the Cancer Genome Atlas (TCGA) databases, we found that aurora kinase A (AURKA) expression is positively correlated with CD276 expression." (PMID 39928563, 2025). "AURKA is a core member of CDC20-M, MLN8237 is a AURKA inhibitor and kill temozolomide-resistant primary glioma cells." (PMID 37682144, 2023). "We also confirmed that alisertib revealed anti-glioma activity in the GBM22 orthotopic PDX model, revealing smaller tumors following treatment with the Aurora kinase A inhibitor." (PMID 34471141, 2021). "A synthetic lethality screen of 714 kinases in pediatric gliomas identified checkpoint kinase 1 (CHK1) and aurora kinase A (AURKA), both MYC stabilizing proteins, and usage of a small molecule inhibitor of AURKA (VX-689) exhibited potent cell killing in vitro." (PMID 30340362, 2018). "As expected, treatment with siRNAs (AURKA siRNA2 and NDC80 siRNA3) significantly decreased the Ki-67 expression and the malignant proliferation of glioma cells." (PMID 26468983, 2015).
glioma (continued). "Knockdown of AURKA and NDC80 by siRNAs suppressed Ki-67 expression and proliferation of gliomas cells." (PMID 26468983, 2015). "What’s more, the combination of AURKA inhibitor (alisertib) and anti–B7-H3 antibody markedly reduced tumor size and promoted CD8+ T cell infiltration and activation in mouse orthotopic syngeneic glioma models." (PMID 39928563, 2025). "We examined several biomarkers that are not routinely used in glioma IHC detection and found that TRIB3 and AURKA were associated with poor prognosis of the disease." (PMID 39118481, 2024). "Besides, the positive correlation between Pontin and six E2F1 targets (AURKA, CDK1, CDK4, CCNA2, CCNB2, E2F8) assessed by GEPIA in glioma further supported the positive regulation of E2F1 targets expressions by Pontin." (PMID 33542204, 2021). "Studies have also shown that in human gliomas, expression of FBXW7β mRNA is specifically suppressed and plays a key role in the pathogenesis of glioma with increased expression of CCNE1, Myc, and AURKA." (PMID 30791487, 2019). "Given that AURKA has been proposed as a potential therapeutic target in glioblastoma, these findings suggest that inhibition of CEP55–AURKA signaling could be a novel strategy for the treatment of glioma and glioblastoma." (PMID 34944109, 2021). "In non-RT cancer cells, such as cervical cancer and glioma cells, loss of SNF5 failed to increase the expression of AURKA, and inhibition of AURKA expression did not sensitize these cells, suggesting that synthetic lethality between SNF5 and AURKA is cancer type-specific." (PMID 34050264, 2021). "A recent study has demonstrated that AURKA could confer self-renewal capacity of competing away the binding of AXIN from β-catenin, inducing β-catenin stabilization and activating Wnt signaling in glioma-initiating cells." (PMID 30405856, 2018). "However, knockdown of AURKA (or NDC80) did not affect the NDC80 (or AURKA) expression in glioma cells." (PMID 26468983, 2015). "The analysis of Repository for Molecular Brain Neoplasia Data (REMBRANT) revealed strong negative correlation between SIX3 and AURKA and between SIX3 and AURKB in glioma." (PMID 28595628, 2017).